ENSG00000289731 (FAM153B)
Gene: Protein-coding gene on chromosome 5 (176,058,717 to 176,159,271, forward strand). Ensembl gene ENSG00000289731.
Homologues: Paralogues in human: FAM153A (79% identical).
Diseases named in the same sentence as ENSG00000289731 in open-access papers:
ENSG00000289731 is named in the same sentence as 3 diseases in open-access papers, as found by Europe PMC text mining. Sharing a sentence is not in itself a finding about the gene and the disease.
ENSG00000289731 shares sentences with these, for which no sentence is quoted: Alzheimer disease (1 paper); Ataxia (1); dementia (1).